GRK5 (G protein-coupled receptor kinase 5)
Diseases named in the same sentence as GRK5 in open-access papers (continued):
Sharing a sentence is not in itself a finding about the gene and the disease.
tumor (16 papers, 2009 to 2025). "We assessed the loss-of-function effect of GRK5 on tumor cell self-renewal using the sphere assay on a panel of ARMS (Rh5 and Rh30) and ERMS (381T and SMS-CTR) cell lines." (PMID 32363002, 2020). "We assessed the loss-of-function effect of GRK5 on tumor cell growth using an ATP-based viability assay on a panel of ARMS (Rh5 and Rh30) and ERMS (381T and SMS-CTR) cell lines." (PMID 32363002, 2020). "Several reports underline the involvement of GRK5 in the regulation of tumor growth even if they appear controversial." (PMID 27326393, 2016). "Several reports underline the involvement of GRK5 in the regulation of tumor growth." (PMID 27326393, 2016). "Research has shown that whereas GRK5 expression in the cytoplasm suppresses tumor growth, its presence in the nucleus promotes the formation of tumors." (PMID 38638965, 2024). "Through functional assays in vitro and in vivo, we show that GRK5 regulates cell cycle in a kinase-independent manner to promote RMS tumor cell growth." (PMID 32363002, 2020). "GRK5 regulates cell cycle progression to promote ERMS tumor cell growth in a kinase-independent manner." (PMID 32363002, 2020). "Treatment of human RMS xenografts in mice with CCG-215022, a GRK5-selective inhibitor, results in reduced tumor growth and self-renewal in both major subtypes of RMS." (PMID 32363002, 2020). "Treatment of RMS xenografts with a selective GRK5 inhibitor, CCG-215022, results in a significant reduction of tumor growth, demonstrating the potential of GRK5 as a therapeutic target in RMS." (PMID 32363002, 2020). "It has been shown that GRK5 is involved in tumor growth and progression even if its effect is quite controversial." (PMID 30524659, 2018). "Depletion of GRK5 inhibits A549 and H1299 cell proliferation, migration in vitro, and xenograft tumor formation in vivo." (PMID 29463786, 2018). "In this review, we discuss these different effects of GRK5 on tumor progression, and the different molecular mechanisms by which GRK5 exerts these effects." (PMID 27326393, 2016). "In this context, further studies will be needed to better define the nuclear effects of GRK5 and the possibility to regulate its subcellular localization in order to regulate its functions within the tumor cell as necessary." (PMID 27326393, 2016). "Similar results were seen in the analysis of the TCGA database where GRK3 and GRK5 again showed lower expression levels in tumor cells compared to normal breast tissue." (PMID 27049755, 2016). "This study demonstrates the ability of the RH domain of GRK5 to inhibit tumor growth through NFκB antagonism." (PMID 19900276, 2009). "In vitro, adenovirus mediated GRK5-RH overexpression (AdGRK5-NT) in human tumor cells (KAT-4) induces IκB accumulation and inhibits NFκB transcriptional activity leading to apoptotic events." (PMID 19900276, 2009). "Furthermore, LINC01315 was also a tumor promoter of TNBC that modulated the progression of TNBC via modulating miR-876-5p/GRK5." (PMID 35412954, 2022). "Further study is required to determine whether GRK5 directly or indirectly interacts with NFAT1 in ERMS in regulating ERMS tumor cell growth." (PMID 32363002, 2020). "G protein-coupled receptor kinase 5 (GRK5) plays an important role in tumor cells’ proliferation." (PMID 30344926, 2018). "As expected, the A549 cell proliferation and tumor formation in vivo was dramatically retarded compared with that of scramble shRNA-transformed cells, and both tumor weights and volumes in the A549 GRK5 knockdown cells were less than those of A549-scramble shRNA cells." (PMID 29463786, 2018).
tumor (continued). "On the other hand, given the anti-tumor effect of GRK5, exploring the putative compound or other molecular events that induce the upregulation of GRK5 could be more effective." (PMID 29463786, 2018). "In addition, the Ki67 IHC staining in the xenograft tumor tissues showed that the GRK5 knockdown indeed inhibited cancerous cell proliferation in vivo." (PMID 29463786, 2018). "However, its role in tumor growth is still complex and ambiguous, since GRK5 exerts opposite effects, depending on tumor cell type and kinase localization within the cell." (PMID 27326393, 2016). "Results suggest that adenoviral mediated GRK5-RH expression inhibits NFκB activity in tumor cells." (PMID 19900276, 2009). "Thus, it is likely that GRK5 could regulate tumor growth also through the regulation of TRK and Frizzled receptors." (PMID 27326393, 2016). "Consequently, we propose that targeting GRK5 could not only attenuate the proliferation and spread of TC but also enhance the tumor’s immune response, making it a potentially effective therapeutic target for the development of anti-tumor immunotherapy in TC." (PMID 40722845, 2025). "TN stage correlation analysis demonstrated BGN, GRK5 and SREBF1 were closely correlated tumor progression." (PMID 34116604, 2021). "The expression of GRK5 or ACTC1 in all of the matched paratumor tissues was set as 1.00 ± 0.00, and the expression in each of the tumor tissues was compared with that in the matched paratumor tissues." (PMID 35223984, 2021). "Using a high-throughput siRNA screen against the human kinome, we identified GRK5, a G-protein receptor kinase, as a novel regulator of RMS tumor cell growth and self-renewal." (PMID 32363002, 2020). "However, it is still unclear whether GRK5 plays any role during NSCLC tumor progression." (PMID 29463786, 2018). "We therefore tested in a human tumor cell line, KAT-4, the effects of GRK5-RH on cell growth either in cultured cells or in tumors in BALB/c nude mice, grown after subcutaneous injection of KAT-4 cells." (PMID 19900276, 2009). "While these mechanisms require validation in TC, our findings that GRK5 inhibition (i) enhances APC-mediated immune responses and (ii) synergizes with T-cell cytotoxicity position it as a master regulator of tumor-immune crosstalk." (PMID 40722845, 2025). "In particular, GRK5's subcellular location affects both its inhibitory and promotive actions; therefore, the type of tumor is not the only factor affecting them." (PMID 38638965, 2024). "In addition, we demonstrated that knockdown of GRK5 inhibited NSCLC cell proliferation, migration in vitro, and xenograft tumor formation in vivo by promoting cell cycle arrest at G2/M phase and inducing cellular apoptosis." (PMID 29463786, 2018). "In addition, we found that depletion of GRK5 inhibited NSCLC cancerous cell proliferation, migration in vitro, and xenograft tumor formation in vivo." (PMID 29463786, 2018). "Second, our data demonstrate that GRK5 suppression substantially elevates TNF-α and IFN-γ, cytokines that induce MHC class I/II expression; this suggests GRK5 may dampen tumor immunogenicity by suppressing antigen presentation machinery." (PMID 40722845, 2025). "However, when GRK5 moves to cytosol or nucleus, it often promotes tumor growth acting on nonreceptor substrates." (PMID 35223984, 2021). "Moreover, non-visual GRK member investigations have shown that GRK5 and GRK3 act completely differently in a variety of tumor types." (PMID 38638965, 2024).
cardiovascular diseases (10 papers, 2018 to 2026). "GRK5 is also associated with other blood pressure regulation-related cardiovascular diseases such as myocardial infarction or cardiometabolic traits such as hyperlipidemia." (PMID 38961282, 2024). "Lastly, dysregulation of GRKs (G-protein-coupled receptor kinases) can be associated with pathological conditions including cardiovascular disease, and GRK5 was found to form a complex with CUL4 through DDB1 and undergo CUL4•DDB1-dependent ubiquitination." (PMID 35327608, 2022). "In addition, we identified several interesting candidates such as Taf4b, Tmc8, Wdr11, and Grk5 that were previously associated with different chronic metabolic and inflammatory diseases including T2D, cardiovascular disease, and/or IBD69,70,74,76,77,80,81." (PMID 36788222, 2023). "GRK5 has also been proposed as a therapeutic target for cardiovascular disorders, making it an attractive candidate for drug repurposing." (PMID 40040803, 2025). "Several studies have investigated the role of GRK5 in cardiovascular diseases, including, importantly, its effect on MI." (PMID 41515937, 2025). "G-protein coupled receptor kinase 5 (GRK5) belongs to a family of serine/threonine kinases and plays an important role in cardiovascular disease pathogenesis and early heart development." (PMID 32363002, 2020). "Thus, GRK5 represents a potential promising target for treatment strategies not only of total-, and particularly LDL-cholesterol levels, but possibly also of cardiovascular disease." (PMID 29773828, 2018). "Three different GRK isoforms (GRK2, GRK5, and GRK3) and two β-adrenoceptors (β1-AR and β2-AR) are present in peripheral blood mononuclear cells (PBMC) and their expression changes as a consequence of the hemodynamic and neurohumoral alterations that occur in some cardiovascular diseases." (PMID 30837872, 2019). "G protein-coupled receptor kinase 5 (GRK5) also plays a complex role in both tissue repair and maladaptive hypertrophy in cardiovascular diseases; however, its effect on NF-κB-mediated inflammation has not yet been elucidated." (PMID 41515937, 2025). "More specifically, the interaction of GRK5 with non-GPCR proteins has been shown to profoundly influence transduction pathways controlling both CNS and cardiovascular disease trajectories." (PMID 30618771, 2018).
cardiac diseases (7 papers, 2018 to 2025). "In this review, after a brief description of cardiac β-ARs, we discuss the pathophysiological roles of GRK2, GRK5, and Epac1 in cardiac disease." (PMID 33466800, 2021). "Among downstream signals of β-ARs, compelling evidence indicates that GRK2, GRK5, and Epac1 represent attractive therapeutic targets for cardiac disease." (PMID 33466800, 2021). "Additionally, our findings implicate GRK5 as a promising therapeutic target for cardiac diseases." (PMID 41515937, 2025). "Thus, cardiac GRK5 stimulation (e.g., via β2AR activation) might be of therapeutic value for heart disease treatment via boosting the efficacy of MR antagonists against Aldo-mediated cardiac injury." (PMID 32326036, 2020). "Although various reports have demonstrated the function of GRK5 in cardiac diseases, the role of GRK5 in MI has not yet been elucidated." (PMID 36633120, 2023). "In that vein, PKA inhibition or GRK5 stimulation in cardiomyocytes may augment the beneficial effects of MR antagonists in heart disease, since PKA activates and GRK5 inhibits cardiac MR transcriptional activity." (PMID 30486399, 2018).
metabolic disease (4 papers, 2018 to 2025). A congenital disorder (due to inherited enzyme abnormality) or acquired (due to failure of a metabolically important organ) disorder resulting from an abnormal metabolic process. "GRK2 and GRK5 have already been proposed as potential drug targets in metabolic disease including T2D." (PMID 36030052, 2022). "Data linking GRK5 with metabolic disorders in humans are sparse." (PMID 29773828, 2018). "Despite several reports relating GRK5 expression levels with neurodegenerative, cardiovascular, and metabolic diseases, we have not found significant alterations in GRK5 mRNA when comparing cells expressing wt- or p.Phe508del-CFTR or across DMSO versus 9g or ETI." (PMID 40040803, 2025).
infection (1 paper, 2013). The state of being infected such as from the introduction of a foreign agent such as serum, vaccine, antigenic substance or organism. "On the second day following infection, cells were treated with DMSO or CDZ for 1 hr, fixed, and stained for GRK5." (PMID 23472081, 2013).
neurodegenerative disease (1 paper, 2018). A disorder of the central nervous system characterized by gradual and progressive loss of neural tissue and neurologic function. "This review has focused on one such GRKs, i.e., GRK5 and in particular, the capacity of GRK5 to mediate a signaling connection between cardiovascular and neurodegenerative disease." (PMID 30618771, 2018). "In this review, we discuss the role of GRK5 in the context of cardiovascular and neurodegenerative disease to emphasize its function in inflammaging." (PMID 30618771, 2018). "However, the complete ramifications of the correlation between GRK5 levels to different cardiac and neurodegenerative disease etiologies, across the human lifespan, still remains to be determined." (PMID 30618771, 2018).
GRK5 also shares sentences with these, for which no sentence is quoted: lung carcinoma (3 papers); adenocarcinoma (2); asthma (2); atrial fibrillation (2); inflammation (2); Insulin resistance (2); acute kidney injury (1); cystic fibrosis (1); Epithelial Ovarian Cancer (1); escherichia coli infection (1); glioma (1); hypertrophic cardiomyopathy (1); hypertrophy (1); Impaired glucose tolerance (1); ischemia (1); Kaposi's sarcoma (1); neurological diseases (1); opioid dependence (1); rectum adenocarcinoma (1); rhabdomyosarcoma (1); squamous cell carcinoma (1); Stroke (1); substance abuse (1); Synthesis (1); systolic heart failure (1); tendinopathy (1); teratospermia (1); thrombosis (1); type 1 diabetes- (1); uveal melanoma (1).
A further 2 diseases each share a sentence with GRK5 in 1 paper.